STAB1 (stabilin 1)
Diseases named in the same sentence as STAB1 in open-access papers (continued):
Sharing a sentence is not in itself a finding about the gene and the disease.
atherosclerosis (8 papers, 2021 to 2026). A disease characterized by the build-up of fatty material and calcium deposition in the arterial wall resulting in partial or complete occlusion of the arterial lumen. "For example, CTSW has been studied for its role in HDL cholesterol metabolism and its potential impact on atherosclerosis, while STAB1 has been implicated in the clearance of atherogenic lipoproteins." (PMID 38384714, 2024). "Double‐knockout mice (Stab‐DKO) develop impaired kidney function and a decreased lifespan, while single Stabilin deficiency or therapeutic inhibition ameliorates atherosclerosis and Stab1‐inhibition is subject of clinical trials in immuno‐oncology." (PMID 37357460, 2023). "While targeted inhibition of Stab1 or Stab2 might be beneficial in the context of atherosclerosis prevention, double deficiency leads to premature organ failure likely due to multi‐ligand depositions caused by deficient hepatic scavenging." (PMID 37357460, 2023). "Similarly, Scavenger Receptors Stabilin-1 and Stabilin-2 were associated with atherosclerosis, and inhibition of Stabilin-1/Stabilin-2 can significantly reduce Erg1 expression in mononuclear macrophages, thus reducing the progression of atherosclerosis." (PMID 37123263, 2023). "Utilizing bulk RNA sequencing, six core efferocytosis-related genes (STAB1, ANO5, GULP1, LGR6, SCARF1, and CAMK2G) were identified, which exhibit significant diagnostic potential in atherosclerosis." (PMID 42272635, 2026). "Stab1 and Stab2 have been shown to influence fibrosis in liver and kidneys and to modulate inflammation in atherosclerosis." (PMID 38946049, 2024). "Stab1 and Stab2 single inhibition mediates beneficial effects in atherosclerosis development, anti‐Stab1 inhibition is in clinical trials in immune‐oncology." (PMID 37357460, 2023). "Only recently, we were able to show that single Stabilin inhibition reduces atherosclerosis development, furthermore, anti‐Stab1 antibodies are in initial clinical trials as an immunomodulatory cancer treatment." (PMID 37357460, 2023). "Furthermore, EMP-derived macrophages expressed high levels of stabilin 1 (Stab1) and growth arrest specific 6 (Gas6), both of which are important for efferocytosis, a process crucial for the inhibition of atherosclerosis." (PMID 34759917, 2021). "Since anti-Stab1 therapies are already in Phase I/II clinical trials and Stab1/Stab2 inhibition has therapeutic promise in atherosclerosis, non-homeostatic disease models of genetic Stabilin deficiency might allow predicting side-effects of anti-Stabilin antibodies." (PMID 37446152, 2023).
COVID-19 (8 papers, 2021 to 2024). A disease caused by infection with severe acute respiratory syndrome coronavirus 2. "Subsequently, three key genes (CDKN1A, IFI27, and STAB1) were screened using machine learning to predict the occurrence of COVID-19 related IIM." (PMID 37638007, 2023). "In this context, autoantibodies such as ACE2-aab, AGTR2-aab, BDKRB1-aab, CXCR3-aab, MAS1-aab, CHRM5-aab, NRP1-aab, F2R-aab, STAB1-aab appeared to play a major role in stratifying COVID-19 by disease burden." (PMID 35264564, 2022). "Interestingly AABs to the vaso- and immunoregulatory receptors CXCR3, CHRM5, BDKRB1, MAS1, AGTR1, F2R/PAR-1, and STAB1 were the most significant classifiers of acute COVID-19 severity in our recent study." (PMID 36238301, 2022). "Thus, elevated CD36 and STAB1 gene expression may indicate increased oxidized lipoproteins uptake during severe COVID-19 and this in turn partially could explain lipid profile abnormalities observed in our study as well as in others." (PMID 36758022, 2023). "As part of the diagnostic investigations, we introduced the measurement of a panel of antibodies against GPCR receptors and 2 other molecules potentially involved in reactions to COVID-19 and vaccines: ACE2 and STAB1." (PMID 39767757, 2024). "Classification using random forest indicated AABs targeting ADRB2, STAB1, and ADRA2A as the strongest classifiers (AABs stratifying patients according to disease outcomes) of post COVID-19 outcomes." (PMID 36238301, 2022). "All genes (PPARG, CD36, STAB1, ITGAV, and ANXA2) downregulated in surviving patients with COVID-19 are related to cholesterol homeostasis." (PMID 34944005, 2021). "mRNA copy counts were determined for the STAB1 gene in non-survived patients with COVID-19, survived patients with COVID-19 in 7 days after admission to the ICU and in control individuals." (PMID 36758022, 2023). "However, ddPCR did not reveal the differences in expression level of the STAB1 gene between controls and survived patients with COVID-19 (p>0.05) in 7 days after admission to the ICU." (PMID 36758022, 2023).
liver fibrosis (8 papers, 2019 to 2024). "In disease processes such as liver fibrosis or arteriosclerosis, reduced clearance functions by loss of Stab1 are further exaggerated." (PMID 38275881, 2024). "Our findings here give further insights into the scavenging of fasciclin domain proteins TGFBi and POSTN, which are heavily implicated in liver fibrosis and hepatocellular carcinoma, through Stab1 and Stab2 and in liver fibrosis models." (PMID 37446152, 2023). "Interestingly, Stab1 deficiency aggravates liver fibrosis upon chronic liver injury using CCl4 and six weeks of MCD diet as models." (PMID 37446152, 2023). "It has been shown that the combined knockout of Stab1 and Stab2 (Stab1/Stab2−/−) leads to severe renal glomerulofibrosis, albuminuria mild perisinusoidal liver fibrosis and premature death of mice." (PMID 38946049, 2024). "Previous studies have shown that the scavenger receptor, stabilin-1 protects against liver fibrosis by enabling macrophages to eliminate fibrogenic products of lipid peroxidation." (PMID 39700261, 2024). "To conclude, we show how liver fibrosis in preclinical models differentially correlates with TGFBi and POSTN levels in response to deficiency for Stab1 or Stab2, bearing consequences for potential anti-Stabilin therapies." (PMID 37446152, 2023). "In contrast, deletion of both, Stab1 and Stab2, resulted in premature mortality with severe glomerular kidney fibrosis and only mild liver fibrosis and dysfunction." (PMID 33745018, 2021). "In experimental models of liver fibrosis, stabilin-1 promotes the uptake of products of chronic oxidative stress by a subset of hepatic macrophages and suppresses their release of pro-inflammatory mediators that regulate tissue remodelling." (PMID 31315308, 2019). "While Stab1-deficient (Stab1−/−) mice were shown to exhibit higher liver fibrosis levels upon challenges, fibrosis susceptibility has not been studied in Stab2-deficient (Stab2−/−) mice." (PMID 37446152, 2023). "Similar to sinusoidal capillarization in liver fibrosis and cirrhosis, transdifferentiation of the sinusoidal vasculature is observed in human and murine HCC with loss of LSEC markers STAB1, STAB2, LYVE-1, CD32b, and GPR182 and induction of the continuous EC marker CD31." (PMID 33745018, 2021). "We showed that impaired clearance of GDF-15 in STAB-1–/–STAB-2–/– mice leads to severe glomerular fibrosis and mild perisinusoidal hepatic fibrosis." (PMID 34975851, 2021).
colorectal cancer (5 papers, 2013 to 2024). A primary or metastatic malignant neoplasm that affects the colon or rectum. "In patients with advanced colorectal carcinoma (CRC) or gastric cancer, higher levels of Stab1-positive macrophages correlated with decreased tumor-specific survival." (PMID 38275881, 2024). "The probable cell-type specificity is similar to other potential molecular diagnostics and prognostics methods such as special AT-rich sequence-binding protein 1 (STAB1) expression, beta-catenin alterations and microsatellite instability (MSI) in colorectal cancer." (PMID 24325735, 2013).
glioblastoma (5 papers, 2016 to 2024). The most malignant astrocytic tumor (WHO grade IV). "Additionally, the Scavenger Receptor Stabilin-1 (STAB1), identified as a receptor for the matricellular protein SPARC involved in glioblastoma cell migration, highlights its potential significance in cancer development and response to treatments like REGO, necessitating further exploration." (PMID 38534332, 2024).
Sepsis (5 papers, 2019 to 2025). Sepsis is defined as life-threatening organ dysfunction caused by a dysregulated host response to infection. "HNF4A promotes M2 macrophage polarization via the NCOA2/GR/STAB1 axis and attenuates acute-phase gene expression, with its activation linked to improved outcomes in models of sepsis." (PMID 41169395, 2025). "Knockout (KO) mice for Stab1 are more susceptible to the lethal effects of Coxsackievirus B3-induced myocarditis, sepsis, or Listeria infection." (PMID 37510214, 2023). "Consistent with this, stabilin-1 deficiency causes a decrease in survival in an animal model of sepsis, which is associated with reduced phagocytosis and increased vascular permeability." (PMID 31434355, 2019). "The regulatory axis of HNF4A/NCOA2/GR/STAB1 could potentially serve as a therapeutic target for sepsis-associated lung damage." (PMID 39979267, 2025). "Overall, this study revealed that the regulatory axis of HNF4A/NCOA2/GR/STAB1 affects macrophage polarization, thereby improving sepsis-induced lung damage." (PMID 39979267, 2025). "In the context of sepsis, where the pro-inflammatory response predominates, STAB-1 was previously proposed to be both an immunosuppressive player to downregulate hyper-inflammation at early stages and to act as a vascular barrier keeper in later stages of sepsis." (PMID 34374322, 2021). "Furthermore, stabilin-1–mediated phagocytosis is inhibited by HMGB1 (high-mobility group box 1), a pro-inflammatory mediator of organ damage in sepsis." (PMID 31434355, 2019).
bladder cancer (4 papers, 2020 to 2024). "STAB1 has an association with bladder cancer and acute myelogenous leukemia." (PMID 35460704, 2022). "Stabilin-1 is expressed by endothelial cells and M2 macrophages, participates in receptor-mediated endocytosis and intracellular transport, has been proposed to serve as a prognostic marker for bladder cancer, and may confer resistance to immune checkpoint cancer therapies." (PMID 38979184, 2024).
hepatocellular carcinoma (4 papers, 2018 to 2025). A malignant tumor that arises from hepatocytes. "However, in de-differentiated tissues in cases of liver cancer, loss in the expression of Stabilin-1 and -2 was seen in hepatocellular carcinoma (HCC) patients, and this loss was inversely related to patient survival." (PMID 32848838, 2020). "During hepatocellular carcinoma (HCC) progression in humans, LSECs lose the expression of their markers, including lymphatic vessel endothelial hyaluronan receptor-1 (LYVE-1), CD32b, stabilin-1, and stabilin-2." (PMID 40595432, 2025).
Obesity (4 papers, 2015 to 2024). Accumulation of substantial excess body fat. "If STAB1 overexpression is a marker for obesity, hypermethylation in this gene could be associated with a leaner body type in the veterans, similar to that of the French women chronically exposed to TCDD." (PMID 33849548, 2021). "Stabilin-1 (STAB1) and triggering receptor expressed on myeloid cell 2 (TREM2) are expressed in a lipid-associated macrophage subset, which supports a tumor immunosuppressive microenvironment and is involved in the progression of obesity and its metabolic complications." (PMID 37033267, 2023).
fibrosis (3 papers, 2023 to 2024). the formation of excess fibrous connective tissue in an organ or tissue in a reparative or reactive process. "Levels of TGFBI in the liver correlate with the intensity of perisinusoidal fibrosis in Stab1 KO." (PMID 38275881, 2024).
gastric cancer (3 papers, 2020 to 2025). A primary or metastatic malignant neoplasm involving the stomach. "CD163 and Stabilin-1, as M2-associated markers, were used to localize macrophages in gastric cancer tissues." (PMID 32226513, 2020). "An independent study evaluating the effects of STAB1 in gastric cancer also noted that STAB1+ TAMs expressed significantly higher HLA-DR levels resulting in higher grade tumors." (PMID 41007347, 2025).
leukemia (3 papers, 2020 to 2025). A malignant (clonal) hematologic disorder, involving hematopoietic stem cells and characterized by the presence of primitive or atypical myeloid or lymphoid cells in the bone marrow and the blood. "STAB1 as another example was also significantly up-regulated in M3 subtype (FDR <7.84e-89, FC = 5.46), and reducing expression inhibits the growth of NB4 leukemia cells." (PMID 38322990, 2024). "Although the role of TSPAN2, STAB1 and MBTPS1were not confirmed in leukemia, they were reported to be involved in the progression of the tumor metastasis." (PMID 31892991, 2020).
lung carcinoma (3 papers, 2022 to 2024). "In the lung carcinoma allograft model, tumors are also smaller in the absence of STABILIN-1, and this reduction in size is even more surprising if Stabilin-1 is inactivated only on macrophages." (PMID 36230610, 2022).
metastatic tumors (3 papers, 2018 to 2021). "It has also been shown that stabilin-1-deficient mice had smaller primary and metastatic tumors than wild-type controls." (PMID 31302753, 2020).
ovarian carcinoma (3 papers, 2017 to 2023). A malignant neoplasm originating from the surface ovarian epithelium. "Among genes previously linked to ovarian cancer, tests of LIME1, GPR162, STAB1, and SKAP1 resulted in unadjusted p-values <0.05." (PMID 34449791, 2021). "Among 86 genes linked to ovarian cancer in previous publications, our data contained expression values for 42, and of these, tests of LIME1, GPR162, STAB1, and SKAP1, resulted in unadjusted p<0.05." (PMID 34449791, 2021).
schizophrenia (3 papers, 2020 to 2025). A major psychotic disorder characterized by abnormalities in the perception or expression of reality. "In this way, we found one gene stabilin 1 (STAB1) might contribute to schizophrenia susceptibility previously identified by pathway analysis." (PMID 32066673, 2020). "At the gene level, both STAB1 and ANK3 have been associated with bipolar disorder and schizophrenia." (PMID 41211100, 2025).
urothelial bladder cancer (3 papers, 2016 to 2025). "In urothelial bladder cancer, a higher abundance of STAB1+ TAMs is linked to increased mortality following transurethral resection." (PMID 41007347, 2025). "This study investigates the relationship between the density and microlocalization of stabilin-1+ Mφs within tumors and the clinical outcomes of patients with urothelial carcinoma of the bladder (UCB)." (PMID 31302753, 2020). "In a cohort study on urothelial bladder cancers, the expression of STAB1 on TAMs but not lymphatic endothelial cells correlated with poor response to neoadjuvant chemotherapy and reduced overall survival." (PMID 41007347, 2025).
breast tumor (2 papers, 2016 to 2020). "Moreover, studies on mouse models have shown that the expression of stabilin-1 induced tumor growth and helped tumor cells acquire invasive capability by endocytosis of antitumoral matricellular glycoprotein SPARC in breast tumors." (PMID 31302753, 2020). "In contrast, we demonstrate that expression of stabilin-1 on TAM directly isolated from breast tumor microenvironment is not accompanied by major changes in expression profile as assessed by gene microarray analysis." (PMID 27105498, 2016).
diabetes (2 papers, 2017 to 2024). "Adachi and Tsujimoto found that SNX17 directly interacted with FEEL-1/stabilin-1, which was implicated in the development of diabetes." (PMID 28744461, 2017). "Specifically, genes such as CCL17, CD163, APOE, CYP27A1, and STAB1, some of which are recognized as anti-atherogenic and anti-inflammatory factors in diabetes patients, were identified within this module." (PMID 38658734, 2024).
infarction (2 papers, 2022). A localised pathological necrosis of tissue resulting from obstruction of the blood supply usually by a thrombus, an embolus, or vascular torsion. "A high number of CD68+ cells in the red pulp and reduced concentration of stabilin-1+ cells in the white pulp were associated with unfavorable post-infarction outcomes." (PMID 35629341, 2022). "According to our previous results, stabilin-1+ cells are involved in post-infarction myocardial remodeling, but its content was assessed only in myocardial tissue." (PMID 35629341, 2022).
liver disease (2 papers, 2019 to 2023). "In this review, we focus on the role of stabilin-1 in two key processes that contribute to liver disease, namely, the recruitment of lymphocytes into liver tissue and the response of macrophages to tissue injury." (PMID 31315308, 2019). "A very high correlation of TGFBi to overall fibrotic burden was observed in the liver, indicating that loss of Stab1 or Stab2 alone does not seem to impede scavenging of POSTN or TGFBi, even in liver disease models in these mice." (PMID 37446152, 2023).
mammary adenocarcinoma (2 papers, 2016 to 2024). "Further, a full KO of Stab1 also significantly decreases the growth of murine mammary adenocarcinoma." (PMID 38275881, 2024). "Using stabilin-1 knockout (ko) mice we show that stabilin-1 facilitates growth of mouse TS/A mammary adenocarcinoma." (PMID 27105498, 2016). "Using stabilin-1 knockout mice we demonstrated that the absence of stabilin-1 on TAM results in reduced growth of TS/A mammary adenocarcinoma which is accompanied by impaired endocytic clearance function of TAM and reduced uptake of SPARC capable of inducing TS/A tumor cell death." (PMID 27105498, 2016).
metabolic syndrome (2 papers, 2016 to 2023). A cluster of metabolic risk factors for CARDIOVASCULAR DISEASES and TYPE 2 DIABETES MELLITUS. "Furthermore, a number of genes within the RNO16 differential segment associated with metabolic syndrome components in human studies showed polymorphisms between SHR and BN-Lx (including Lpl, Nrg3, Pbx4, Cilp2, and Stab1)." (PMID 27031336, 2016). "Seven metabolic syndrome-related genes (CSF3R, TMEM132A, STAB1, VIM, DUOXA1, PILRB, and SLC2A4) were used to construct risk equations." (PMID 37033267, 2023).
Parkinson’s (2 papers, 2019 to 2024). "Replication in the International Parkinson's Disease Genomics Consortium (IPDGC) confirmed the association with PD risk for three out of the six identified variants (STAB1 p.S1089G, SH3GL2 p.G276V, and NOD2 p.G908R) (p < 10−3)." (PMID 31920912, 2019).
acute lymphoblastic leukemia (1 paper, 2025). Leukemia with an acute onset, characterized by the presence of lymphoblasts in the bone marrow and the peripheral blood. "Among the different malignancies, the results indicated high expression of STAB1 mRNA in nearly all AML samples and in a subset of the myeloproliferative disease samples (MDS), T- and B-cell lymphoma samples, as well as in pre-B-cell acute lymphoblastic leukemia." (PMID 40369178, 2025).
arthrogryposis multiplex congenita (1 paper, 2025). Arthrogryposis multiplex congenita (AMC) is a group of disorders characterized by congenital limb contractures. "Some symptoms of a defective STAB1 gene overlap with those of a Arthrogryposis Multiplex Congenita, namely neurodevelopmental disorders." (PMID 40565278, 2025).
Autoimmunity (1 paper, 2025). The occurrence of an immune reaction against the organism's own cells or tissues. "Their enrichment in Fate 1 implies that HPV infection may trigger interferon-driven autoimmunity, accompanied by STAB1/TRIM22 upregulation." (PMID 41035636, 2025).
Cognitive impairment (1 paper, 2022). Abnormal cognition is characterized by deficits in thinking, reasoning, or remembering. "As the AAB targets F2R/PAR-1, CXCR3, and STAB1 are involved in inflammatory processes this finding points to a distinct inflammatory mechanism in cognitive impairment in PCS/ME/CFS in contrast to vasoconstriction in the previous cohort of non-COVID ME/CFS." (PMID 36238301, 2022).